ZNF878 (zinc finger protein 878)
Description:
May be involved in transcriptional regulation.
Tractability: PROTAC: ubiquitination databases record sites on it.
Gene: Protein-coding gene on chromosome 19 (12,040,992 to 12,052,972, reverse strand). Ensembl gene ENSG00000257446.
Subcellular location: Nucleus
Subcellular location (Human Protein Atlas): Nucleoplasm; Nucleoli
Gene Ontology:
Molecular function: DNA-binding transcription factor activity, RNA polymerase II-specific; RNA polymerase II transcription regulatory region sequence-specific DNA binding
Biological process: regulation of transcription by RNA polymerase II; regulation of DNA-templated transcription
Cellular component: nucleus
Genetic constraint (gnomAD): Loss-of-function variants: 9 observed, 9.76 expected, observed/expected ratio (o/e) 0.92, 90% interval 0.55 to 1.59. That is too few expected variants to judge how well the gene tolerates losing a copy. Missense variants: 547 observed, 645.92 expected, observed/expected ratio (o/e) 0.85, 90% interval 0.79 to 0.91. Synonymous variants: 165 observed, 216.94 expected, observed/expected ratio (o/e) 0.76, 90% interval 0.67 to 0.87.
Homologues: Orthologues: chimpanzee ZNF878 (93% identical), macaque ZNF878 (91% identical), mouse Zfp867 (43% identical), rat Zfp867 (42% identical). Paralogues in human: ZNF700 (61% identical), ZNF709 (61% identical), ZNF433 (60% identical), ZNF791 (57% identical), ZNF14 (56% identical), ZNF443 (54% identical), ZNF44 (54% identical), ZNF799 (53% identical), ZNF823 (53% identical), ZNF441 (52% identical), ZNF442 (52% identical), ZNF844 (42% identical), and 3 more.